CRP (C-reactive protein)
Diseases named in the same sentence as CRP in open-access papers (continued):
Sharing a sentence is not in itself a finding about the gene and the disease.
dementia (continued). "A recent US cohort reported that CRP was related to a faster rate of cognitive decline and a higher risk of dementia across a 10-year follow-up." (PMID 37190623, 2023). "In the context of chronic inflammatory diseases, the arising dilemma concerns the dynamics related to the penetration of the BBB by systemic CRP, which proceeds to infiltrate the brain and potentially cause dementia." (PMID 36776896, 2023). "Long-term assessment of circulating CRP/mCRP can be considered as a precious tool to enable estimation of an individual’s relative risk of developing dementia." (PMID 36776896, 2023). "The association between high CRP levels and incident dementia differed across minoritized and racialized group." (PMID 37066239, 2023). "In a longitudinal study which comprised participants aged over 90 years, it was demonstrated that elevated CRP values were associated with increased odds of all-causes dementia." (PMID 36776896, 2023). "A recent large study of Alzheimer’s disease and all forms of dementia linked low plasma CRP with greatest risk of disease." (PMID 37048104, 2023). "CRP and the associated risk of dementia and further research indicated that the monomeric form of CRP can infiltrate the BBB/be released from damaged micro-vessels to access the brain." (PMID 36776896, 2023). "For example, among minoritized participants, high CRP was associated with 1.27 (95% CI: 1.01, 1.59) times higher risk of incident dementia than low CRP." (PMID 37066239, 2023). "This is inconsistent with previous studies which described higher CRP levels related to impaired cognitive performance in older adults and to increased risk 25 years later of dementia." (PMID 36915478, 2023). "C-reactive protein (CRP) is an acute-phase inflammatory molecule that has drawn interest as a potential biomarker of underlying cognitive health and dementia." (PMID 37190623, 2023). "Of these three inflammatory markers, CRP has been associated with progression to dementia even after adjustment for confounding factors, while IL-6 has been specifically associated with vascular dementia." (PMID 37239136, 2023). "In our models, biological age was defined as a composite measure derived from residual LTL adjusting for chronological age, inflammation (CRP) and 46 curated chronic comorbidities including risk factors of dementia." (PMID 37061546, 2023). "Sequential adjustment suggested that the strength of the association between high CRP levels and dementia risk increased after conditioning on potential confounders." (PMID 37066239, 2023). "Statins have been shown to reduce C-reactive protein (CRP) concentrations while elevated CRP are associated with dementia." (PMID 36135833, 2022). "Mediation analyses indicated that part of the inverse association between late-life BMI and dementia risk was mediated by higher levels of CRP, where higher BMI is associated with higher CRP levels, which are in turn inversely associated with dementia." (PMID 36192662, 2022). "An increased levels of peripheral inflammatory markers, such as IL-6, TNF-α, or C-reactive protein (CRP), were found to be associated with future cognitive decline and dementia." (PMID 35631163, 2022). "This study investigates the combined effect of CRP and HbA1c, as well as the influence of dietary patterns, on the risk of dementia." (PMID 35252292, 2022). "The association between CRP and dementia also appears to have a paradoxical and age-specific pattern, similar to that of overweight and dementia." (PMID 36192662, 2022). "Several studies have found increased levels of pro-inflammatory cytokines and proteins like interleukin-6 (IL-6), interleukin-1β (IL-1β), C-reactive protein (CRP), or α1-antichymotrypsin (α1-AT) to be associated with the onset of all-cause dementia." (PMID 36085081, 2022).
dementia (continued). "In the multivariable model, four independent variables were independently associated with the presence of delirium: dementia, followed by age at admission, C-reactive protein (CRP), and Glasgow Coma Scale." (PMID 35204633, 2022). "Factors independently associated with the risk of delirium included older age, GCS, presence of dementia, and CRP." (PMID 35204633, 2022). "In late-life, a higher BMI is associated with lower risk of dementia, with a substantial proportion of the association mediated through CRP levels while the association is suppressed by lower levels of HDL-c." (PMID 36192662, 2022). "In the multivariable analysis, only four variables were retained in the model as independently associated: dementia showed the highest predictive value, followed by age at admission, CRP, and GCS." (PMID 35204633, 2022). "Accordingly, a previous meta-analysis study indicated that inflammation markers like Interleukin-6 and C-reactive protein are related to an enhanced risk of dementia." (PMID 35444524, 2022). "The mediation decomposition of the BMI-CRP-dementia association indicated a significant pure indirect effect of CRP, which mediated 37% of the inverse association between BMI and dementia risk." (PMID 36192662, 2022). "A meta-analysis of 8 prospective studies concluded that higher CRP levels are associated with increased risk of incident dementia, with stronger effects in studies with longer follow-ups." (PMID 36192662, 2022). "A systematic review and meta-analysis found that elevation of peripheral CRP levels was associated with increased risk of developing dementia." (PMID 34572280, 2021). "In support of this, the Honolulu-Asia Aging Study (HAAS) demonstrated that elevated serum CRP levels in midlife increased the risk of developing dementia later in life." (PMID 34884906, 2021). "The MD has been associated with lower levels of C-reactive protein and interleukins, previously found to increase the risk of major forms of dementia such as AD and vascular dementia." (PMID 33671575, 2021). "Elevated CRP peripheral blood levels have been frequently associated with increased risk of dementia and cognitive decline." (PMID 34572280, 2021). "Our finding suggests that CRP is a modifiable risk factor of dementia that responded to mindfulness intervention in specifically older adults with MCI, consistent with prior findings shown in other sample populations." (PMID 32066726, 2020). "Another avenue for further research are inflammatory markers such as C-reactive protein, interleukin-6, and α1-antichymotrypsin, which have shown predictive value for the onset of all-cause dementia." (PMID 32116848, 2020). "Serum levels of IL-6 and CRP in patients with acute ischemic stroke and underlying dementia (AIS + D) were significantly higher (p = 0.002 and 0.003, respectively) than in patients with acute ischemic stroke alone (AIS)." (PMID 32758167, 2020). "In Parkinson’s disease dementia, another form of dementia associated with Lewy bodies, a rise in c-reactive protein has been identified, after the onset of dementia." (PMID 30403785, 2018). "Those with both the ApoE4 allele and chronic low-grade inflammation demonstrated a CRP level–dependent pattern that was linked to increased risk of AD and dementia." (PMID 30646251, 2018). "Monomeric CRP has been discussed as a linker between vascular damage and inflammation on the one hand and plaque formation, neuronal damage, and dementia risk on the other." (PMID 29482610, 2018). "Secondary outcomes will include body mass index, body composition, fasting blood lipids, C-reactive protein, fasting plasma glucose, fasting serum insulin, erythrocyte fatty acids, cognitive function, psychological health and well-being, and dementia risk." (PMID 29273039, 2017). "Delirium is related to several risk factors as higher age, dementia, disability on admission, and increased CRP." (PMID 28828209, 2017).
dementia (continued). "Our use of stricter statistical methods helped to identify more reliable risk factors (mainly dementia, severe neurological disability as well as CRP on admission and age) and challenged results of other studies." (PMID 28828209, 2017). "In another meta-analysis, higher peripheral concentrations of C-reactive protein (CRP) and IL-6 were associated with an increased risk of all-cause dementia whereas the association with risk of AD alone was weak." (PMID 28464009, 2017). "Inflammatory markers, including circulating CRP, have been associated with risk of dementia and cognitive decline in the elderly." (PMID 27259001, 2017). "Serum or plasma biomarkers of inflammation, especially IL-6 and C-reactive protein (CRP), were prospectively associated with cognitive decline in multiethnic cohorts of older populations before the clinical onset of dementia, AD, and vascular dementia." (PMID 26682220, 2015). "Systemic inflammation is generally considered a risk factor for dementia, but in studies of ApoE ε4 allele carriers CRP has been inversely correlated with both all-cause dementia and levels of CMV IgG." (PMID 24804776, 2014). "The higher level of CRP associated with apolipoprotein E4 has been reported to exacerbate the susceptibility of dementia and cognitive impairments." (PMID 24044608, 2013). "C-reactive protein (CRP), a systemic marker of inflammation, is a risk factor for late life cognitive impairment and dementia, yet the mechanisms that link elevated CRP to cognitive decline are not fully understood." (PMID 22461977, 2012). "The long-term prospective association between dementia and the well known inflammation marker CRP was evaluated in a cohort of Japanese American men." (PMID 15904534, 2005). "Compared with men in the lowest quartile (<0.34 mg/L) of high-sensitivity CRP, men in the upper three quartiles had a 3-fold significantly increased risk for all dementias, mainly Alzheimer's disease and vascular dementia." (PMID 15904534, 2005). "Recently, an association between inflammatory markers alpha 1-antichymotrypsin, interleukin 6, and, to a lesser extent, C-reactive protein were associated with an increased risk of dementia." (PMID 15476562, 2004). "High levels of IL6 and CRP in plasma are a risk factor for dementia." (PMID 40699836, 2025). "During the development of this study, various associations were made, with the most significant being the strong link between the ApoE4 allele and chronic low-grade inflammation (as indicated by CRP measures), which was strongly associated with an increased risk of AD and dementia." (PMID 40519469, 2025). "The precise role of CRP in multimorbidity‐related dementia risk thus remains unresolved." (PMID 40990184, 2025). "Interestingly, elevated markers of systemic inflammation (such as IL-6 and CRP) have been linked to increased dementia risk, even decades prior to its occurrence, possibly due to accelerated accumulation of amyloid-β." (PMID 41403901, 2025). "Furthermore, studies have also linked increased CRP levels to an elevated risk of dementia and depression, highlighting the potential impact of inflammation on cognitive decline and mental health." (PMID 40534869, 2025). "Besides, high plasma levels of C-reactive protein at baseline were associated with a high risk of all incident dementia in this study, which is corresponded with the result of the latest research." (PMID 40009844, 2025). "However, elevated CRP was significantly associated with an increased risk of progression from normal cognition to dementia (HR = 1.473, p = 0.0394; adjusted HR = 1.429, p = 0.010)." (PMID 41373439, 2025). "Furthermore, MAP improved inflammatory biomarkers such as CRP, IL-6 and IL-1β, showing its potential to target biological pathways associated with dementia." (PMID 40563752, 2025).
dementia (continued). "Higher CRP levels have been linked to poorer global cognitive performance in healthy older adults, and are associated with an increased risk of developing dementia 25 years later." (PMID 39807297, 2025). "However, it is unclear why the association between C-reactive protein and incident dementia was stronger in APOE4 carriers than in non-APOE4 carriers." (PMID 38378514, 2024). "Further, an unmeasured confounder associated with both high CRP and incident dementia with approximate rate ratios of 1.06-fold could shift the mediated proportion confidence interval to the null, but a weaker confounder could not." (PMID 39003383, 2024). "However, among Hispanic participants, high CRP was associated with 1.85 (95% CI: 1.27, 2.70) times higher risk of dementia than low CRP." (PMID 39003383, 2024). "CRP, which is a sensitive indicator of inflammation that is easily measurable in clinical settings, has already been associated with cognitive impairment and was shown to be a predictive marker of dementia in healthy older adults." (PMID 38840166, 2024). "Relevant data have shown that CRP levels are associated with dementia and schizophrenia." (PMID 38053016, 2023). "Supporting this notion, in a recent 10-year longitudinal study, increased CRP levels has been linked to worse future cognitive function only among cognitively healthy older participants; while in patients with dementia, elevated CRP was associated with slower future cognitive decline." (PMID 37593375, 2023). "Age, sex, BMI, low hemoglobin level, time from injury to admission, time from injury to surgery, type of hip fracture, CHD, dementia, pulmonary disease, kidney disease, smoking, fibrinogen, C-reactive protein, and albumin were considered independent risk factors for DVT." (PMID 36615152, 2023). "Further, an unmeasured confounder associated with both high CRP and incident dementia with approximate rate ratios of 1.05-fold could shift the mediated proportion confidence interval to the null, but a weaker confounder could not." (PMID 37066239, 2023). "This and the fact that serum CRP levels change, may explain the observed weak associations between CRP and dementia." (PMID 37467176, 2023). "Interestingly, contradictory results were yielded from Cox and RCS analysis regarding the association between CRP and risk of dementia." (PMID 38071240, 2023). "However, among Hispanic participants, high CRP was associated with 1.55 (95% CI: 1.06, 2.27) times higher risk of dementia than low CRP." (PMID 37066239, 2023). "Meanwhile, the systemic inflammatory response to acute stroke involves increased CRP, which may be associated with the development of cognitive decline and dementia." (PMID 37509012, 2023). "Inflammation and oxidative stress are implicated in the pathogenesis of dementia; there is evidence suggesting that the loss of skeletal muscle is associated with high levels of inflammatory markers such as interleukin-6 and CRP." (PMID 35013908, 2022). "Moreover, increased C-reactive protein and IL-6 are associated with dementia, identified by a meta-analysis combining seven observational studies (5,717 participants and 746 dementia cases)." (PMID 36344931, 2022). "However, a meta-analysis of cross sectional studies shows that CRP levels are lower in individuals diagnosed with mild or moderate dementia, compared to controls, indicating that the association differs before and after disease onset." (PMID 36192662, 2022). "In addition, two prospective cohort studies previously examined change in CRP level with dementia and cognition, which suggesting low plasma CRP level were also associated with high risk of dementia and cognitive impairment." (PMID 35927253, 2022). "In this context, the determination of CRP could be used in the future as a component of risk calculations for the development of dementia, in addition to the quantification of NF-L and BACE1 as well as epigenetic and protein-based methods." (PMID 36358351, 2022).
dementia (continued). "Elevated concentrations of inflammatory markers in the systemic circulation, such as C-reactive protein (CRP) and IL-6, are associated with the risk of dementia, although local inflammation in the CNS and systemic inflammation are suggested to contribute to cognitive decline." (PMID 35661882, 2022). "Elevated CRP levels are associated with an increased risk of cerebrovascular diseases and dementia." (PMID 35054785, 2022). "Statin treatment is associated with a reduction in serum cytokine levels and C-reactive protein levels that might lower the risk of dementia in patients with RA." (PMID 33879179, 2021). "This was, for example, surprising for the inflammation marker CRP, since this biomarker has, longitudinally, been linked to physical frailty, cognitive decline, and risk of dementia, and therefore could serve as a biomarker for cognitive frailty." (PMID 31214102, 2019). "Inflammation has been however more consistently associated with risk of dementia, suggesting markers such as CRP may be better predictors for later stage of neurodegeneration but do not have great predictive value for mild cognitive impairment." (PMID 29462285, 2019). "On these bases, it has been suggested that CRP may mirror the inflammatory process in the brain and described that higher CRP levels are associated with increased risk of dementia." (PMID 31181792, 2019). "Using unspecific and specific CRP antibodies against mCRP, immunoreactivity has been detected in the neurofibrillary tangles of AD patients and elevated CRP concentrations have been associated with increased risk of developing dementia in older people." (PMID 30254628, 2018). "Similarly to several other inflammatory markers, elevated peripheral blood levels of CRP have frequently been associated with increased risk of dementias and cognitive decline in multiple studies, although less robustly with AD itself." (PMID 29482610, 2018). "Furthermore, the acute phase protein, serum C-reactive protein (CRP), is associated with greater risk of dementia onset and memory impairment, and has also been found to co-localise with pathological Aβ and neurofibrillary tangles in the brains of AD patients." (PMID 29892788, 2018). "Using χ2 analyses, we tested whether the association between ApoE genotype and chronic low-grade inflammation status with the risk for incident dementia including AD and mortality changed when using different CRP cutoff levels." (PMID 30646251, 2018). "MCI appears to be a risk factor for developing dementia as shown by a Chinese study in which about 30% of patients with MCI developed dementia within 2 years and high plasma C-reactive protein levels were associated with accelerated cognitive decline and increased risk of dementia." (PMID 28638339, 2017). "Regardless, lowering CRP still further in ε4 carriers might be expected to have adverse effects on dementia risk, given our present findings." (PMID 28291794, 2017). "After adjustment for baseline characteristics, including sex, age, baseline UPDRS-III score, and dementia, baseline CRP was found to be significantly associated with change in UPDRS-III score [regression coefficient = 1.41 (95% CI 0.21–2.61), P = 0.021] (Model II)." (PMID 26308525, 2015). "High levels of CRP have been reported to be associated with the development of dementia in patients with mild cognitive impairment, so cognitive function might also be associated with CRP levels." (PMID 24497930, 2014). "In a longitudinal analysis of blood from approximately 900 subjects, higher protein levels of three inflammatory markers (interleukin 6, α1-antichymotrypsin, and C reactive protein) were associated with an increased risk of dementia in general and of AD specifically." (PMID 23705665, 2013). "IL-6 and C-reactive protein (CRP) correlated with accelerated functional decline in the elderly, and middle age CRP levels may prognosticate dementia risk." (PMID 23924506, 2013).